MUC16 (mucin 16, cell surface associated)
Diseases named in the same sentence as MUC16 in open-access papers (continued):
Sharing a sentence is not in itself a finding about the gene and the disease.
cancer (continued). "In this study, we have described the development and the preclinical evaluation of 89Zr-DFO-M16Ab as a PET imaging probe of MUC16-expressing cancers." (PMID 36559316, 2022). "Pan-carcinoma results show that except in BRCA, the MUC16 is more highly expressed in other cancers tissues." (PMID 35281840, 2022). "EOC cancer patients exhibited higher levels of MUC16 bound to T cells, NK cells and B cells compared to healthy controls." (PMID 35219339, 2022). "For instance, MUC16 (CA125) is a well-known cancer biomarker contributing to disease progression and metastasis in several malignancies." (PMID 36059804, 2022). "Antibodies that recognize cancer biomarkers, such as MUC16, can be used as vehicles to deliver contrast agents (imaging) or cytotoxic payloads (therapy) to the site of tumors." (PMID 36559316, 2022). "In comparison to other antibody-based immunoPET probes developed against CA125/MUC16, we developed a fully human monoclonal antibody for the non-invasive imaging of MUC16-expressing cancers." (PMID 36559316, 2022). "MUC16 is a well-known cancer biomarker and has becomes a potential target for therapy in recent years." (PMID 35681552, 2022). "Transmembrane mucins such as MUC1 and MUC16 are also thought to facilitate the metastasis of many carcinomas by binding to mesothelin in recipient tissues." (PMID 36497364, 2022). "Transmembrane mucins such as MUC1 and MUC16 are also thought to facilitate the metastasis of many carcinomas including pulmonary adenocarcinomas." (PMID 36497364, 2022). "MUC16 is known to promote the progression and metastasis of a variety of malignant tumors, and the abnormal expression of MUC16 can lead to drug resistance to cytotoxic drugs and inhibition of apoptosis." (PMID 34386035, 2021). "The first has been proven to be necessary for the survival of MYC-driven cancers, whereas several studies have confirmed the role of MUC16 in cancer progression." (PMID 34683922, 2021). "We here summarize the detailed tumorigenic roles of MUC1 and MUC16 in the context of cancer hallmarks." (PMID 34681277, 2021). "Of these, NCOR1, MUC4, and MUC16 genes have been investigated for their aberrant expression in various cancers and being attractive targets for immunotherapy in previous studies." (PMID 33504001, 2021). "In the four groups of samples, the majority of the genes were enriched in various cancer-related pathways, immunity pathways and signal transduction pathways, which indicated the significant role of the MUC16 gene in HCC." (PMID 34150633, 2021). "It was a peptide epitope of a membrane-spanning mucin MUC16 which promoted cancer cell proliferation and inhibited anti-cancer immune responses." (PMID 34178632, 2021). "In this review, we discuss the biological roles of the transmembrane mucins MUC1 and MUC16 in the context of hallmarks of cancer and current efforts to develop MUC1- and MUC16-targeted therapies." (PMID 34681277, 2021). "MUC16 is an important membrane protein that maintains normal cell function and has a role in cancer development." (PMID 34150633, 2021). "MUC16, also known as carbohydrate antigen (CA) 125, is often used as a serum diagnostic and prognostic biomarker for PDAC and other cancers, in combination with other well-known markers such as CA19-9 and carcinoembryonic antigen (CEA)." (PMID 34522225, 2021).
cancer (continued). "This therefore represents a rational target for therapeutic applications in MUC16-expressing cancers." (PMID 33580170, 2021). "MUC16 increases the invasion, migration, and proliferation of cancer cells in vitro, and also enhances tumorigenesis and metastasis in vivo." (PMID 34635181, 2021). "MUC16 is overexpressed in several cancers including ovarian, pancreatic, breast, and lung, and has been shown to be associated with cancer progression and poor prognosis." (PMID 34880292, 2021). "MUC16 protein promotes invasive behavior in preclinical models of cancer, both in vitro and in vivo." (PMID 34965417, 2021). "MSLN is known to bind to mucin 16 (MUC16/CA125), which is expressed by MPM cells and is associated with cancer progression and aggressiveness." (PMID 34439085, 2021). "In MUC16-expressing cancer cells, 14D11 treatment blocked AKT and ERK1/2 phosphorylation, and led to inhibition of cancer cell Matrigel invasion." (PMID 33580170, 2021). "MUC16 or mucin 16 is a 132 kb gene coding for mucin protein which is a glycoprotein involved in cancers and SSPO (subcommissural organ spondin) is a 58 kb gene that codes for a protein involved in neuronal aggregation." (PMID 34722422, 2021). "Msln-mediated secretion of MMP-7 in MUC16-expressing cancer cells occurs via a p38 MAPK-dependent pathway." (PMID 34966784, 2021). "Despite these limitations, this observed association between MUC16 mutation and ICI response in this pan-cancer study represents a further step toward the development of factors associated with outcomes for ICI therapy in solid tumors." (PMID 32845327, 2020). "Upon malignant transformation, many types of cancer cells express high levels of sialic acids and cancer-associated glycans (e.g., mucins (MUC1 and MUC16), Sialyl-Tn (sTn)) on their surfaces or secrete them to the extracellular media." (PMID 33333862, 2020). "Their failure is thought to be due to soluble MUC16 acting as a sink for mAb binding and failure of the mAb to reach the cancer cells." (PMID 32937961, 2020). "Some mucins have been used or proposed as biomarkers for carcinomas, such as MUC16 (CA125) and MUC4." (PMID 32175327, 2020). "MUC16 is a useful marker not only for clinical diagnosis but also for prognosis: MUC16 overexpression on the surface of cancer cells is correlated with poor outcome in pancreatic, colon and EOC patients." (PMID 30795761, 2019). "Due to the large mass of MUC16, only a limited amount has been revealed about its mechanism and function in cancer." (PMID 30795761, 2019). "The cancer cells expressing low levels of MUC16 on their surface are the preferential target for the Natural killer (NK) cells, contributing to immunoediting." (PMID 29588543, 2018). "Strikingly, only OVCAR3 and OVCAR4 expressed MUC16 at levels similar to SOCs (i.e., >75% of cancer cells stained)." (PMID 30011875, 2018). "For the 19 Mucin (MUC) family genes, nine of them were RMGs and four of them (MUC17, MUC5B, MUC4, and MUC16) were common RMGs shared in 8 to 17 cancer types." (PMID 30107644, 2018).
cancer (continued). "Using MUC16 CT transfected cells we and others have shown that the MUC16 CT confers tumorigenic, metastatic, and anti-apoptotic, properties to cancer cells and contribute to therapy resistance, however the underlying mechanisms remain poorly understood." (PMID 29708979, 2018). "This was validated in quantification of plasma and ascitic fluid MUC16/CA125 antigen levels using the Cancer Antigen CA125 Human ELISA Kit." (PMID 30287783, 2018). "CA125 is a repeating peptide episode of the mucin MUC16, which promotes cancer cell proliferation and inhibits anti-cancer immune responses." (PMID 29849940, 2018). "MUC16 is known to promote cancer invasion and metastasis and inhibits host immune responses by directly down regulating the activity of NK cells." (PMID 29708979, 2018). "In fact, we recently showed that this high-affinity ligand/receptor interaction was associated with a rapid and selective accumulation of MesoTR3 and Meso64TR3 on MUC16-expressing cancer targets." (PMID 29267342, 2017). "CP, SCEL, and MUC16 had positive coefficients with a log2 ratio >1 for advanced T, N stage and perineural invasion cancer tissue." (PMID 28423673, 2017). "As a result, we found 3 novel candidate genes (CP, SCEL, and MUC16), having positive coefficients with a log2 ratio >1 for advanced T, N stage and perineural invasion cancer tissue." (PMID 28423673, 2017). "We next used more quantitative means (flow cytometry) to document the selective killing capacity of Meso64-TR3 on MUC16-positive cancer cells." (PMID 27120790, 2016). "According to previous studies, MUC16 can promote tumorigenesis and metastasis while inhibit anti-cancer immune responses." (PMID 27167110, 2016). "Aberrant MUC16 expression can also appear in patients with other types of cancers, including breast, lung and pancreas malignancies." (PMID 27167110, 2016). "During last 30 years, MUC16/CA125 had attracted plenty attention to its clinical application as a cancer biomarker." (PMID 27167110, 2016). "We identified the high affinity of the mesothelin/MUC16 interaction as the dominant parameter for the rapid attachment of targeted TR3 fusion proteins to MUC16-positive cancer cells with the TR3/DR interaction playing a secondary role." (PMID 27120790, 2016). "Our data provides important, novel information on cytokines as factors driving MUC16 expression in cancer cells and possibly in normal tissues as well." (PMID 26918940, 2016). "The previous experiments provided circumstantial evidence for the activation of the extrinsic death pathway being responsible for the improved properties of Meso64-TR3 on MUC16-positive cancer cells." (PMID 27120790, 2016). "Serial sections of a human cancer tissue array were stained simultaneously using anti-MUC16 or anti-TNFα or anti-IFNγ antibody." (PMID 26918940, 2016). "Human cancer tissue microarray analysis indicated that MUC16 expression directly correlates with TNFα and IFNγ staining intensities in certain cancers." (PMID 26918940, 2016). "If this was true, we anticipated that MUC16-positive cancer cells should be preferentially eliminated from a heterogeneous mix of positive and negative cells." (PMID 27120790, 2016). "In this study, we built on our previously established drug platform TR3 and generated a truncation variant of Meso-TR3, designated Meso64-TR3, representing a functionally improved, next generation TRAIL-based cancer therapeutic targeted to the biomarker MUC16." (PMID 27120790, 2016). "MUC16 is believed to play important roles not only in normal contexts such as reproduction, but also in pathological states including cancer and mucosal infections." (PMID 26918940, 2016). "We demonstrated that MUC16-Cter imparts proliferative, invasive and chemo resistance properties to PC cancer cells in vitro in addition to enrichment of ALDH+ CSCs." (PMID 25691062, 2015). "MUC16 (CA125) is a type-I transmembrane glycoprotein that is up-regulated in multiple cancers including pancreatic cancer (PC)." (PMID 25691062, 2015).
cancer (continued). "As a result of enhanced aerobic glycolysis, cancer cells exhibit enhanced lactate secretion, so we further evaluated the effect of MUC16 knockdown on lactate secretion." (PMID 26046375, 2015). "Since expression of MUC16 protein is an important driver of cancer behavior, we examined the impact of MUC16 copy number on MUC16 mRNA expression." (PMID 25965947, 2015). "In particular, we have identified the glycosylated MUC16 ectodomain as critical to MUC16 alterations in cancer cell behavior." (PMID 25965947, 2015). "The relevance of the mesothelin/MUC16 interaction for attaching Meso-TR3 to the cancer cells was verified by competitive blocking experiments using soluble mesothelin." (PMID 24447304, 2014). "Cell-surface bound as well as soluble MUC16 is overexpressed in human ovarian tumor cells and detected in peritoneal fluid of cancer patients." (PMID 24592356, 2014). "As a result, those cancer cells with high levels of MUC16, the subset that is most likely to resist immune attack, survive." (PMID 24886523, 2014). "CA125 is a repeating peptide epitope of the mucin MUC16, which promotes cancer cell proliferation and inhibits anti-cancer immune responses." (PMID 24886523, 2014). "MUC16 knockdown causes a decrease in the expression of matrix metalloproteases (MMP-2), a class of proteolytic enzymes that plays a crucial role in cancer cell metastasis." (PMID 24886523, 2014). "The mechanism by which MUC16 inhibits NK cell-mediated killing of cancer cells is under investigation." (PMID 24886523, 2014). "Even after MUC16 knockdown, E- and L-selectin binding is observed to cancer cells, presumably via other glycolipid, mucin, or glycoprotein ligands." (PMID 24886523, 2014). "Meso-TR3 was characterized for binding selectivity and killing efficacy against MUC16-positive cancer cells and controls that lack MUC16 expression." (PMID 24447304, 2014). "Knockdown of MUC16 inhibits in vitro and in vivo proliferation of cancer cells MUC16-triggered activation of STAT3 via JAK2 results in increasing cancer cell proliferation." (PMID 24886523, 2014). "This type of protection can occur from interaction of the NK and monocyte Siglec-9 with MUC16 on the surface of cancer cells and also from circulating MUC16 molecules cleaved from the cancer cells via proteolysis." (PMID 24886523, 2014). "Our discussion of the biological role of MUC16 will focus on its importance in cancer cell signaling, metastasis, regulation of immune responses and on anti-cancer therapeutic strategies that target this mucin." (PMID 24886523, 2014). "We have proposed that NK cells contribute to immune editing by selectively lysing cancer cells expressing lower levels of MUC16." (PMID 24886523, 2014). "To convert TR3 (center) into a MUC16-targeted cancer drug, we inserted the entire cDNA of soluble mesothelin (including the N-terminal FLAG tag) to the 5′-terminus of a TR3 expression plasmid (Meso-TR3)." (PMID 24447304, 2014). "Initially we tried to establish MUC1 and MUC16 ZFN KOs of the cancer cells, but difficulties in generating the ZFN MUC1 and MUC16 KO cells prevented us from using this approach (data not shown)." (PMID 24039759, 2013). "By combining measurements of the standard CA 19-9 assay with detection of CA 19-9 on MUC5AC and MUC16, the sensitivity of cancer detection was improved relative to CA 19-9 alone in each sample set, achieving 67–80% sensitivity at 98% specificity." (PMID 22220206, 2011). "We and others have shown that MUC16, present on the surface of cancer cells, binds readily to mesothelin." (PMID 20350313, 2010). "Following proteolytic cleavage, cell surface MUC16 (csMUC16) is shed in the extracellular milieu and is detected in the serum of cancer patients as the tumor marker CA125." (PMID 20497550, 2010). "MUC16 is increased in multiple cancer types, playing important roles in their tumorigenicity." (PMID 40806007, 2025).
cancer (continued). "Cancer vaccines aim to stimulate the immune system to recognize and attack tumor-specific antigens, offering a promising strategy for OC, which expresses well-defined targets such as CA-125 (MUC16), NY-ESO-1, and WT1." (PMID 40643516, 2025). "However, dysregulation in mucin expressions, such as MUC1, MUC2, MUC4, MUC5AC, and MUC16, have been observed in many cancer cells." (PMID 40699805, 2025). "MUC16 and its extracellular components are often important cancer-related biomarkers." (PMID 38758220, 2024). "MUC16 (mucin 16, cell surface-associated), previously known as carbohydrate antigen 125 (CA125), is a mucin marker that is among the most frequently mutated genes in human cancer tissues." (PMID 39548061, 2024). "Moreover, we classified the high-risk subgroup as a pro-cancer group with lower mutation rates of key genes (SPOP and MUC16), multiple low expression of immune-associated molecules, and differential expression of macrophages (M1 and M2)." (PMID 38643190, 2024). "Further, coating the surface of MUC16 + cancer cells with a high density of IgG may opsonize and trigger antibody-dependent cellular cytotoxicity (ADCC), complement-dependent cytotoxicity (CDC) and other Fc-mediated antitumor effects." (PMID 38225646, 2024). "Cancer treatments for MUC16 cancers are currently at various stages of progress." (PMID 38637885, 2024). "However, during the process of carcinogenesis, when cell polarity is dysregulated, MUC16 is expressed on the cell surface and interacts with various growth factors, and this feature of MUC16 is highly relevant to cancer." (PMID 38637885, 2024). "Mucin-16 (MUC16) is a membrane-bound mucin that is abnormally expressed or mutated in a variety of diseases, especially tumors, and can be regarded as an important cancer-related biomarker." (PMID 39219440, 2024). "Recent studies suggest that MUC16 may play a role in modulating immune responses in different cancers." (PMID 38361923, 2024). "Expression and oncogenic roles of MUC16 in various human cancers." (PMID 38361923, 2024). "Subsequently, prognostic subgroups based on key genes classified the high-risk group as a pro-cancer subgroup that had lower mutation rates of critical genes (SPOP and MUC16), multiple low-expression immune-relevant molecules, and differences in macrophages (M1 and M2) expressions." (PMID 38643190, 2024). "Such antibody treatments target the circulating extracellular domain of MUC16 and may deplete the pool of circulating antibodies available for targeting cancer cells." (PMID 38637885, 2024). "However, we found bright green fluorescent signal on the cell membranes of both OVCAR3 and SKBR3 which express MUC16, indicating that the scFv can specifically bind to native glycosylated MUC16 expressed on cancer cells." (PMID 38374055, 2024). "MUC16/CA125 is one of the few oldest cancer biomarkers still used in current clinical practice." (PMID 36816942, 2023). "In cancer progression, MSLN is known to bind to the cancer antigen MUC16." (PMID 37546424, 2023). "Previous reports indicated that MUC16 and TTN mutations could predict high TMB level and were correlated with favorable prognosis in pan-cancer, including GC." (PMID 38090588, 2023). "During cancer development, MUC16 is aberrantly expressed, both in its amount and glycosylation." (PMID 37455827, 2023).